MIR4520-1 (microRNA 4520-1)
Synonyms: hsa-mir-4520a; MIR4520A; hsa-mir-4520-1; mir-4520-1
Gene: MicroRNA gene on chromosome 17 (6,655,440 to 6,655,509, reverse strand). Ensembl gene ENSG00000264468.
Homologues: Orthologues: chimpanzee MIR4520-1 (100% identical).
Diseases named in the same sentence as MIR4520-1 in open-access papers:
MIR4520-1 is named in the same sentence as 3 diseases in open-access papers, as found by Europe PMC text mining. Sharing a sentence is not in itself a finding about the gene and the disease.
MIR4520-1 shares sentences with these, for which no sentence is quoted: Abdominal obesity (1 paper); Obesity (1); psoriasis (1).